ALK (ALK receptor tyrosine kinase)
Diseases named in the same sentence as ALK in open-access papers (continued):
Sharing a sentence is not in itself a finding about the gene and the disease.
cancer (continued). "The bulk of the patients in our ALK+ study was in advanced stages of cancer (III-IV)." (PMID 36338735, 2022). "While mechanisms leading to ALK inhibitor resistance in cancers with ALK fusion genes have been extensively studied, the mechanisms in tumors containing activating ALK mutations or ALK amplifications are largely unknown." (PMID 35689207, 2022). "Both EGFR and ALK targets are crucial for cancer proliferation." (PMID 35754819, 2022). "Therefore, CAR-T therapy for ALK positive cancers needs to take into account not only the ALK kinase, but also the extracellular structures expressed by more important ALK fusion partners such as EML4 or NPM, among others." (PMID 36591504, 2022). "ALK-TKIs suppress ALK fusion-oriented oncogenic signaling and the growth of ALK-rearranged cancers." (PMID 35301419, 2022). "Screening for ALK rearrangements has become a very important process in treatment decision making for advanced NSCLC and mutation tests of these genes, including their rearrangements, are part of cancer gene therapy strategies for NSCLC patients." (PMID 36401689, 2022). "In addition, the mechanism is further verified by the down-regulation of p-ALK protein, and up-regulation of Acetylated histone 3 (Ac-H3) protein in cancer cells." (PMID 36100230, 2022). "This supports the idea that, at least in adults, the dose of ALK inhibitor for pain conditions could be lower than what is used for treating ALK-positive cancer." (PMID 35608912, 2022). "Thus, treatment-induced adaptive cancer cells were formed allowing for the maintenance of residual tumors upon initial ALK-TKI treatment." (PMID 35228642, 2022). "Anaplastic lymphoma kinase (ALK) has been described in a range of human cancers and is involved in cancer initiation and progression via activating multiple signaling pathways, such as the PI3K-AKT, CRKL-C3G, MEKK2/3-MEK5-ERK5, JAK-STAT and MAPK signal pathways." (PMID 33391411, 2021). "However, over the disease course, cancers tend to develop resistance mechanisms, warranting the switch from first- to second- or third-generation ALK inhibitors." (PMID 33572278, 2021). "ALKAL2 misregulation facilitates ALK receptor tyrosine kinase signaling and drives ALK‐dependent cancer irrespective of oncogenic mutations." (PMID 33411331, 2021). "If AXL kinase plays an important role in DT cell survival in ALK-rearranged cancer, the dual inhibition of ALK and AXL by gilteritinib might delay the emergence of additional acquired resistance and represent an important clinical option." (PMID 33627640, 2021). "This highlights the heterogeneity of STRN‐ALK fusion in response to ALK inhibitors, and could be crucial to help guide therapeutic decisions to achieve maximum benefit in the era of personalized cancer therapy." (PMID 33960639, 2021). "To investigate this, we applied a combined (targeted) therapy strategy to ALK+ ALCL, a non-Hodgkin peripheral T-cell lymphoma that depends on the activity of ALK fusion proteins, which support cancer growth by constant activation of JAK/STAT, RAS/MEK/ERK and PI3K/AKT pathways." (PMID 34503232, 2021). "However, alectinib is clearly effective at blocking signalling over the long‐term treatment because the efficiency of alectinib in ALK+ cancer patients is impressive with a survival of almost 2 years." (PMID 34661367, 2021). "The impact of MAPK pathway in ALK+ cancer has been suggested by various studies." (PMID 34503232, 2021). "EML4-ALK gene fusion is initiated by inversion in the short arm of chromosome 2, which juxtaposes the N-terminal of the EML4 promoter and the kinase domain of the ALK gene, ultimately leading to ligand-independent constitutive activation of ALK and promoting cancer cell proliferation and survival." (PMID 34054126, 2021).
cancer (continued). "Indeed, some cancer associate isoforms such as ALK and RASA3 were shown to play a role in cancer progression while other cancer-specific isoforms such as ERBB2 were found to have a better prognostic value then canonical ERBB2 expression." (PMID 33499898, 2021). "However, cancers harbouring EML4‐ALK V3 tend to respond less well to ALK inhibitors compared with cancers driven by EML4‐ALK V1." (PMID 34661367, 2021). "Molecular testing in DTTs documents a high risk for recurrence of cancer associated with BRAFV600E, RET/PTC 1/3, ALK and NTRK fusions, while the intermediate risk may be related to BRAFK601E, H/K/N RAS and PAX8/PPARγ." (PMID 33922518, 2021). "The complex ALK rearrangements could be attributed to a distinct mechanism, termed chromothripsis, happened at least 2 to 3% of all cancers and often promoted tumorigenesis in a wide variety of tumors." (PMID 34271921, 2021). "Moreover, amplifications of the ALK gene are also a common genetic alteration found in different paediatric cancers." (PMID 34020009, 2021). "In the past decades, due to the advances of cancer genomics, a group of gene alterations is identified as driver gene mutations for LUAD, such as mutations in epidermal growth factor receptor (EGFR), c-MET, KRAS, anaplastic lymphoma kinase (ALK)." (PMID 33386920, 2021). "We strongly recommend performing CD43, CD30, and ALK in any poorly differentiated malignant neoplasm with epithelioid or spindle morphology particularly when multiple markers have failed to confirm a specific lineage (negative S100, CD45, and cytokeratins) to not miss the diagnosis of ALK- ALCL." (PMID 34572893, 2021). "Likewise, the younger age of the patients whose cancers harbored the ALK translocation has been reported by other groups as well." (PMID 34786182, 2021). "ALK has emerged as an attractive target for small-molecule therapy in cancer." (PMID 33452442, 2021). "Nowadays, molecular testing in DTCs suggests a high risk for recurrence of cancer associated with BRAFV600E, RET/PTC 1/3, ALK and NTRK fusions, while the intermediate risk may be related to BRAFK601E, H/K/N RAS and PAX8/PPARγ." (PMID 33922518, 2021). "ALK-positive cancers tend to develop at a younger age and tend to have a better prognosis." (PMID 34503168, 2021). "c-Myc, previously shown to regulate cancer stemness in ALK + ALCL, regulated the SORE6 activity." (PMID 34287231, 2021). "Because combinatory treatment regimens are probably less likely to induce drug resistance, a special focus will be on the combination of ALK inhibitors with drugs that either target downstream signalling pathways or that affect the survival and proliferation of cancer cells in general." (PMID 34575503, 2021). "Tyrosine kinase fusions that contain kinase-encoding genes, such as ALK, ROS1, RET, FGFR1/2/3 and NTRK1, have been detected in various types of cancer, including glioblastoma, melanoma, and carcinomas of head and neck, breast, lung, prostate, bladder, and thyroid gland." (PMID 33557176, 2021). "In particular, signaling mediated by ALK is essential for cancer cell proliferation and survival." (PMID 32344689, 2020). "It remains to be examined if this new ALK-LATS-YAP-PD-L1 axis may also exist in other cancer types and exert its immunosuppressive effect in cancers other than NSCLC." (PMID 32059449, 2020). "NVP-TAE684 is a selective ALK inhibitor which inhibits different downstream signaling transduction molecules in cancer cells, thereby down-regulating cell cycle and cell proliferation regulatory genes, resulting in arresting cell cycle, inhibiting cell proliferation and inducing cell apoptosis." (PMID 32175279, 2020). "Higher non-synonymous TMB correlates with inferior PFS for first-generation EGFR-TKIs in EGFR-driven patients and worse response to pemetrexed/platinum regimen in EGFR/ALK wild-type patients, which has potential clinical implications for cancer treatment but needs corroboration in larger studies." (PMID 32411590, 2020).
cancer (continued). "Anaplastic lymphoma kinase (ALK) is mostly known for its oncogenic role in several human cancers." (PMID 32059449, 2020). "The anaplastic lymphoma kinase (ALK) gene is thought to play a key role in the development and function of the nervous system and chromosomal alterations and gain of function mutations in it have been reported in a plethora of pediatric cancers." (PMID 32164789, 2020). "Other ALK gene alterations, including mutations and amplification, have been identified in various cancer types, although they do not currently represent druggable aberrations in clinical practice." (PMID 32664698, 2020). "Blocking oligomerization of fusion proteins using the structure of cc domain itself is a potential therapeutic approach to treat cancers of ALK-rearrangements in which the ALK fusion partner has a cc domain; however, to date, this approach has not been experimentally tested." (PMID 32300555, 2020). "Recently, various splicing isoforms of ALK have also been identified in cancer." (PMID 32059449, 2020). "Inhibition of ALK with small molecule inhibitors suppresses cell growth of ALK-positive cancers." (PMID 32344689, 2020). "The ALK inhibitors are effective against cancers harboring ALK fusions." (PMID 33262326, 2020). "For cancer of unknown primary, EGFR mutation and ALK fusion were highly enriched in our cohort, which indicate that those tumors might originate from lung." (PMID 32373528, 2020). "ALK inhibition has also been a chemotherapeutic target in treatments of these cancers." (PMID 33062421, 2020). "To test these hypotheses, we investigated the effects of ALK fusion protein monomerization in vitro and in vivo, and cc peptide treatment for the EML4-ALK-positive cells in cultured Ba/F3 and EML4-ALK-positive cancer cell lines." (PMID 32300555, 2020). "If validated in clinical settings, this in silico approach may impact the design of immunotherapy regimens for ALK-altered cancers." (PMID 32059449, 2020). "Both crizotinib and lorlatinib are drugs targeting the cancer‐driven gene ALK." (PMID 32347012, 2020). "ALK inhibitors are widely used in cancer-targeted therapy now." (PMID 33157918, 2020). "Consequently, we postulated that ALK kinase activity is dependent on EML4-ALK dimerization and that cc peptides would provide appreciable antiproliferative activities in ALK-rearranged cancers." (PMID 32300555, 2020). "ALK is a therapeutic target for multiple ALK-altered cancers." (PMID 32059449, 2020). "Therefore, these two patients were likely harboring tumors with mixed histologic types, and their ALK statuses were compared between two histologic types of cancer, perhaps explaining the discrepancy." (PMID 32674491, 2020). "This landmark study demonstrated that humoral immunity against ALK fusion and ALK-WT could be active in ACLC cancer patients." (PMID 32059449, 2020). "However, despite the antitumor activity of crizotinib and other ALK inhibitors, cancer drug resistance develops typically within a few years of treatment." (PMID 31827192, 2019). "A variety of ALK fusion genes resulting in constitutive activation of ALK, which is normally regulated by its extracellular ligand-binding domain in the full-length molecule, have been identified in human cancers." (PMID 31278140, 2019). "Therefore it seems rational to use ALK TKI in combination with therapy targeting the most common pathways activated in cancer." (PMID 30813562, 2019). "More so, by comprehending the molecular similarities throughout the diverse miscellanea of ALK fusion proteins, potential therapeutic targets may present themselves, and thus improve the prognosis of ALK-related cancers." (PMID 31366041, 2019). "In this guideline, we generically name EGFR mutation, ALK translocation, ROS1 translocation, and BRAF mutation as driver oncogenes that might be the direct cause of cancer evolution." (PMID 31049758, 2019).
cancer (continued). "A recent clinical trial (ClinicalTrials.gov Identifier: NCT02034981) has been initiated to assess the efficacy of crizotinib in cancer patients identified with amplication of crizotinib target genes—anaplastic lymphoma kinase (ALK), MET or ROS proto-oncogene 1 (ROS1) positive." (PMID 31766284, 2019). "Importantly, it was recently shown that cancer-associated chromosomal translocations, for example the PML/RARα translocation in acute promyelocytic leukemia, or the EML4/ALK translocation in lung cancer, give rise to so-called fusion circRNAs (f-circRNAs)." (PMID 31052302, 2019). "Targeted therapy has transformed the landscape of treatment options for ALK-positive cancers." (PMID 31334113, 2019). "The associated perturbation of the 3′UTR expression and subsequent translational regulation of fusion genes could provide new opportunities in the treatment of fusion gene driven cancers such as ALK-positive ALCL." (PMID 31052302, 2019). "Interestingly, brigatinib also showed obvious anti-neoplastic activity in several ALK-negative cancer cell lines, suggesting the presence of an ALK-independent anti-cancer mechanism for brigatinib." (PMID 31410188, 2019). "In cancer, translocations involving the ALK gene form nearly 30 different fusion oncogenes." (PMID 30975211, 2019). "The relationship between the cancer driver mutation and mutation load was examined and found that ADC patients with EGFR mutation or ALK fusion had significantly lower levels of mutation burden when compared with EGFR and ALK wild-type population." (PMID 30992440, 2019). "Particularly intriguing was the prediction that GSK3α is a putative ALK substrate in cancer cells." (PMID 29555900, 2018). "In conclusion, we found that ALK signaling-independent AXL overexpression associated with EMT features and CSC properties was commonly involved in the maintenance of cancer survival, and was critical in intrinsic and acquired resistance to first-and second-generation ALK-TKIs." (PMID 29930762, 2018). "Detailed information regarding ALK-targeted cancer therapy is described in another section." (PMID 30404198, 2018). "Some excellent reviews already summarize the ALK fusion proteins found in various types of cancers." (PMID 30400214, 2018). "All together, our data raised the possibility that ALK regulation of GSK3 is a neural crest-specific activity that may have been co-opted during cancer progression." (PMID 29555900, 2018). "It is of interest to test this hypothesis by including more NB tumors and other forms of ALK-expressing human cancer cells in the future studies." (PMID 29535836, 2018). "The activation of ALK is related to the proliferation of malignant tumors." (PMID 29888269, 2018). "Although it cannot represent all the SRCC, the frequency of such fusion is much higher than most of the reported driver mutated and druggable genes in tumorigenesis in other types/subtypes of cancers (e.g., ALK fusion), indicating its important role on tumorigenesis of SRCC." (PMID 29961079, 2018). "In response to adverse events, such as hypoxia or exposure to chemotherapeutic agents, cell survival signals may be induced including the ability to upregulate the expression of ALK, a protein known to promote survival in cancer cells." (PMID 29535836, 2018). "Indeed, targeted therapies directed at constitutively activated oncogenic tyrosine kinases have proven to be remarkably effective against cancers carrying ALK and ROS1 fusions." (PMID 29455670, 2018). "Recent work by our lab demonstrated a critical role for EGFR signaling in ALK+ cancer cells." (PMID 29507657, 2018).
cancer (continued). "Even in the same type of cancer, different ALK fusion proteins have been discovered." (PMID 30400214, 2018). "Anaplastic lymphoma kinase (ALK) is a receptor tyrosine kinase involved in various cancers." (PMID 30004444, 2018). "This suggests AXL and HSP90 inhibitors may be promising therapeutic drugs to overcome drug-tolerant cancer cell subpopulations in ALK-positive NSCLC patients for the reason that ALK-positive NSCLC cells do not live through ALK-TKI therapy." (PMID 29930762, 2018). "Therefore, ALK-rearranged NSCLC cases represent the largest population amenable of therapy with ALK inhibitors than other known ALK-related cancers combined." (PMID 29455642, 2018). "We observed ALK fusions in 20 samples from eight cancer types (5 samples in LUAD)." (PMID 29617662, 2018). "Sensitivity to ceritinib was restored in cancer cells that had undergone EMT and acquired resistance to ceritinib after a drug holiday, suggesting that EMT-mediated resistance is partly reversible and that ALK mutation drives oncogenic addiction." (PMID 29844868, 2018). "We also summarize some recent research advances on ALK fusion proteins in cancers." (PMID 30400214, 2018). "Moreover, an increasing number of novel ALK fusion proteins are being identified in various types of cancers." (PMID 30400214, 2018). "In principle, these peptides could be used for vaccinations against ALK fusion antigens in cancer patients including NSCLC; however, more experimental tests on humanized mouse or clinical trials need to be performed." (PMID 29189709, 2017). "Notably, wild type ALK expression in the neural crest progenitor cells JoMa1 can drive the formation of malignant tumors in nude mice." (PMID 28915608, 2017). "Additionally, it proved that the CETSA assay was a very useful tool to predict crizotinib sensitivity in different ALK-carrying cancer types." (PMID 29143801, 2017). "Therefore, it is crucial to perform further research to understand TKI resistance in ALK+ cancer patients." (PMID 29143801, 2017). "NSCLC represents the leading cause of cancer death throughout the developed world, but the introduction of a novel class of targeted anti-neoplastic agents, EGFR and ALK TKI directed against EGFR and ALK, has significantly changed the therapeutic options available for patients with NSCLC." (PMID 29312572, 2017). "However, as a known feature following targeted therapies, ALK-positive cancer cells were found to evolve and to develop resistance mechanisms against those TKIs." (PMID 29186933, 2017). "In addition, there was a direct association between PARP1 and the key cancer gene of NSCLC: EGFR, ALK in the interaction network of genes." (PMID 29152079, 2017). "We have recently shown that CETSA (Cellular Thermal Shift Assay), a recently described method that allows for the rapid and simple assessment of drug target engagement in a cellular context, is useful in predicting crizotinib sensitivity in ALK-carrying cancer cells." (PMID 29143801, 2017). "Notably, the molecular pathways that are responsible for sensing the therapeutic stress and its relation with autophagy induction in ALK-related cancer cells, still remain to be clarified." (PMID 29186933, 2017). "Thus, miRNA do not only influence the cellular phenotype and pathogenesis of ALK(+) ALCL but they are also emerging as tissue-specific biomarkers with potential clinical applications for both identifying cancer subtypes and developing new therapies." (PMID 28771164, 2017). "As cancer treatment moves from “one-size-fits-all” cytotoxic therapies to more tailored approaches based on specific molecular alterations, tyrosine kinases like ALK will be expected to take center stage as therapeutic targets." (PMID 28895885, 2017). "Dosing antiemetic medications 30 to 40 minutes before cancer treatment may benefit patients who have nausea after taking ALK inhibitors." (PMID 30333935, 2017). "ALK is however, known mainly for its role in various types of cancer." (PMID 28359267, 2017).